RN7SL303P (RNA, 7SL, cytoplasmic 303, pseudogene)
Gene: Miscellaneous RNA gene on chromosome 8 (22,977,877 to 22,978,127, forward strand). Ensembl gene ENSG00000240116.
Homologues: Orthologues: chimpanzee Metazoa_SRP (96% identical), macaque Metazoa_SRP (93% identical). Paralogues in human: RN7SL2 (85% identical), RN7SL1 (84% identical), RN7SL3 (83% identical), RN7SL230P (81% identical), RN7SL45P (81% identical), RN7SL118P (81% identical), RN7SL220P (81% identical), RN7SL7P (81% identical), RN7SL127P (80% identical), RN7SL296P (80% identical), RN7SL47P (80% identical), RN7SL566P (80% identical), and 702 more.